NANOG (Nanog homeobox)
Diseases named in the same sentence as NANOG in open-access papers (continued):
Sharing a sentence is not in itself a finding about the gene and the disease.
tumor (continued). "SP cells showed higher tumor-initiating ability and SP cell showed higher expressions of stem cell-related genes including SOX2, ALDH1A1, KLF4 and NANOG, indicating that SP cells are enriched with CSCs/CICs." (PMID 27418136, 2016). "We observed that only tumor cells expressed GLI1 and NANOG and, importantly, the expression was heterogeneous as seen in cell cultures." (PMID 26189795, 2016). "Knocking down ZEB2 significantly suppressed the percentage of SP cells and DDP resistance by reducing the expression of tumor stemness factors including BMI1, SOX2, NANOG, and OCT4." (PMID 27589832, 2016). "A recent paper by Lee and colleagues documents that CD24 is important for self-renewal of liver TICs and their propensity to form tumours via a complex regulation involving STAT3 and NANOG." (PMID 25932953, 2015). "We have also found out that specific processes leading to induction of reprogramming to pluripotency (depicted by significant overexpression of NANOG, SOX2, and POU5F1) were triggered 20h after the treatment in the tumour cell population exposed to ROS." (PMID 26671576, 2015). "Since NANOG knockdown suppressed mammosphere formation and reduced levels of SOX2 and MUC1 in tumor xengrafts, we next tried to determine if propagation of CD24−/lowCD44+ breast CSC subpopulation in MCF-7 cells is also regulated by NANOG." (PMID 23662114, 2013). "Along with Nanog homeobox (NANOG), these transcription factors are highly expressed in embryonic, progenitor, and tumor stem cells, in contrast to the low levels of expression that are found in differentiated cells." (PMID 23613880, 2013). "Also, OCT4 and NANOG might function as tumor suppressors in RCC indeed." (PMID 21982273, 2011). "NANOG and OCT4 are more significantly overexpressed in poorly differentiated tumours than in well-differentiated tumours." (PMID 20354527, 2010). "Expression of DNMT3B, PIWIL1, NANOG, OCT4, and CDH2 was significantly elevated in tumor samples compared to normal controls (p = 8.33 × 10−45, 1.01 × 10−23, 7.76 × 10−6, 3.22 × 10−54, and 1.82 × 10−22, respectively), indicating strong tumor-specific upregulation of these genes." (PMID 41596471, 2026). "Both simple and multiple linear regression analyses indicated that piR-823 and DNMT3B have a positive regulatory effect on stemness markers (OCT4 and NANOG), while DNMT3B mainly governed EMT-related marker (CDH2) expression, further supporting their involvement in tumor progression and metastasis." (PMID 41596471, 2026). "KLF4, SOX2, and NANOG had low expressions in tumor tissue compared with its adjacent non-malignant (NM) counterpart, while no significant changes were found for c-MYC and OCT4 gene expressions." (PMID 41463190, 2025). "Immunohistochemical staining of tissue samples confirmed high expression levels of PP1γ, YAP1, SOX2, and NANOG proteins in tumor tissues compared to adjacent non-cancerous tissues." (PMID 40626009, 2025). "To evaluate the stemness role in ITAC prognosis, we analyzed, for the first time, the expressions of the Yamanaka factors KLF4, c-MYC, SOX2, OCT4, and NANOG in a cohort of patients with ITAC and investigate their possible roles in influencing tumor properties and survival." (PMID 41463190, 2025). "In addition, we performed immunohistochemistry experiments on BC tissues at different stages and found that with the progression of BC, the expression levels of tumor stemness-related markers (CD44, OCT4, SOX2, NANOG) gradually increased." (PMID 41387479, 2025). "In summary, YBX1 promotes tumor progression through its transcription factor activity, exerting its effects via various downstream targets such as MUC1, CDC25a, NANOG, Kindlin-2, G3BP1, AURKA, SPP1, the EGFR-RAS-MAPK axis, CORO1C, among others, depending on the specific tumor type." (PMID 40799245, 2025).
tumor (continued). "Furthermore, we found that patients with tumor overexpressing KLF4 and NANOG had significantly higher OS compared to those who showed lower KLF4 and NANOG expressions (log-rank, p = 0.049, and p = 0.0005, respectively)." (PMID 41463190, 2025). "WT1 and FOXA1 silencing impaired the tumor-sphere forming ability of neurospheres treated with TMZ, decreased the spheroid frequency and reduced the mRNA expression of the stem markers NANOG, OCT4 and SOX2 (Fig. 4Gleft and right panels)." (PMID 40399259, 2025). "Moreover, knockdown of Circ-0075305 notably facilitated the growth of GC tumor spheres and upregulated CD44 and NANOG expression." (PMID 38714724, 2024). "Additionally, cell fluorescence experiments demonstrated that overexpression of Circ-0075305 significantly inhibited the growth of GC tumor spheres and downregulated the expression of CD44 and NANOG compared to the control group." (PMID 38714724, 2024). "The intricate network of TFs, including SOX2, OCT4, NANOG, KLF4, c-MYC,β-catenin, STAT3, NF-κB, HIF-1α and YAP/TAZ, is central to the maintenance of the stem-likeproperties of GSCs, which in turn drive tumor heterogeneity, therapeutic resistance, andrecurrence." (PMID 38716541, 2024). "Interestingly, in this tumor type PIWIL2 expression negatively correlated with the stem cell markers POU5F1 and NANOG." (PMID 38303021, 2024). "IHC staining of these xenograft tumours for previous stem cell-like markers, compared to the control xenograft tumours, showed that the percentage of CD44, NANOG, SOX9, SOX2 positive cells was reduced in the STC1-silenced group, and STC1 shRNA and circUBA2 co-transfection played a reversal role." (PMID 39103836, 2024). "In contrast, there was no significant increase in NANOG levels in tumor cells selected without cisplatin (N1 to N3)." (PMID 37165076, 2023). "In comparison to the non-tumour epithelium, we observed that the expression levels of SOX-2, NANOG and OCT4 were increased in AME parenchyma, suggesting that these molecules may be involved in the pathogenesis of AME." (PMID 36655039, 2023). "The overexpression of NANOG and BMI1 were correlated with a high tumor grade." (PMID 37627900, 2023). "High expression of SOX-2, NANOG, and OCT4 has been demonstrated in AME, suggesting that these proteins may act together to maintain undifferentiated stem cells in this tumour." (PMID 37559082, 2023). "NANOG also works together with other stemness factors, such as KLF4, MYC, OCT4, or SOX2, to control target genes that have important functions in embryonic stem cells and, plausibly, in tumor cells." (PMID 37165076, 2023). "Moreover, increased phosphorylation of STAT3 and expression of STAT3 target genes, NANOG and C-MYC in CD24+ OCSC, when inhibited with JAK2, induces cytotoxicity in CD24+ cells, reduces tumor metastasis, and prolongs overall survival." (PMID 37445860, 2023). "In addition, miR-135 effectively suppressed tumor growth and metastasis in vivo by down-regulating ZNF217/NANOG." (PMID 37901333, 2023). "The HBx + scrambled shRNA (Scr) and HBx + NANOG + Scr groups had the highest tumor burden, while the other groups showed little to no tumor burden." (PMID 37744383, 2023). "NANOG also works together with other stemness factors, such as MYC, OCT4, KLF4, SOX2, SOCS2, or ALDH1A1, to control a set of target genes that have important functions in embryonic stem cells and, plausibly, in tumor cells." (PMID 35104240, 2022). "To further investigate whether NANOG expression in tumor cells modulates the immune feature of the TME, we treated CT26 P3 tumor–bearing mice with intravenously administered chitosan nanoparticles carrying a Nanog- or GFP-targeting siRNA along with anti–PD-1." (PMID 35104240, 2022). "In addition, metastatic tumor cells also specifically expressed some genes, such as DPPA3, NANOG, CRABP1 and others." (PMID 35494058, 2022). "The CD24 molecule may also regulate NANOG and OCT4 expression, thus stimulating tumor growth and resistance to chemotherapy." (PMID 35269636, 2022).
tumor (continued). "Interestingly, squamous cell markers such as SALL4, NANOG, SOX2, BMI1, OCT3/4, HIWI, ABCG2, CD133, podoplanin, and ALDH1 also correlate with ESCC tumor stages, therapeutic resistance, relapse, and patient prognosis." (PMID 36474162, 2022). "To characterize the role of NANOG in immune-refractory features of the TME in an ICB therapy–refractory tumor model, we first assessed the expression of NANOG in CT26 cells at different rounds of immune selection (P0 to P3) and found a stepwise increase in NANOG expression from P0 to P3." (PMID 35104240, 2022). "Additionally, the expression of transcription factors known to promote tumor stemness (SOX2, OCT4 and NANOG) were significantly downregulated in DCIS cells expressing IPW and rescued when ID2 was expressed." (PMID 35078502, 2022). "Collectively, our results revealed a possible mechanism through which selection imposed by T-cell based immunotherapy triggered complement-resistant phenotypes in the tumor microenvironment (TME), by establishing a firm molecular link between NANOG and CD59 in immune-edited tumor cells." (PMID 35606403, 2022). "We did not see any major differences in the expression of NANOG transcripts between butyrate treated and un-treated Caco-2 cells or between primary tumor and normal tissue samples." (PMID 33471801, 2021). "We were interested in determining whether this difference in time to tumor-initiation within different dilution groups could be correlated with SOX2, OCT4, or NANOG expression." (PMID 33445692, 2021). "Given that NANOG is a core pluripotent TF that induces tumor stemness, POU2F2 induces NANOG expression alone may initiate POU2F2+ hepatocytes to acquire stemness." (PMID 37733361, 2021). "Furthermore, when endogenous ELK-1 was silenced in the primary tumor culture of patient 624 (middle level of ELK-1 expression), CD133, NANOG, SOX2, and POU5F1 levels were all downregulated as compared to scramble RNA control." (PMID 33672811, 2021). "Since NANOG expression appears to play a regulatory role in tumor growth, we suggest that the PKC-NANOG pathway may be involved in tumor development and progression." (PMID 35008480, 2021). "Furthermore, increases in the properties of stem cells were measured by assessing the capacity for tumor formation and performing transcriptional analysis of the OSKM genes (OCT4, SOX2, KLF4 and MYC), NANOG, NES and PROM1." (PMID 34364391, 2021). "Material from the regrown tumor was collected to establish an isogenic model of carboplatin-resistant TNBC (C4O) and gene expression analysis revealed changes in Wnt signaling target AXIN2 and pluripotency and stem markers NANOG, OCT4, SOX2, and LGR5." (PMID 34367990, 2021). "Moreover, other studies have shown that upregulation of NANOG mediates hypoxia-induced resistance to cytotoxic lymphocyte (CTL) lysis, while knockdown of NANOG in hypoxic tumor cells significantly restores CTL-dependent tumor cell killing." (PMID 33422072, 2021). "However, strikingly, a subset of HNSCC patients (33.3%) harbored high expression of NANOG and SOX2 in histologically normal mucosa with comparable levels to the matched tumor." (PMID 32635524, 2020). "Using double immunofluorescence, the colocalization of NANOG protein with pericentrin was identified by two independent anti-NANOG antibodies among 11 tumor and non-tumor cell lines." (PMID 32168958, 2020). "High infiltration of CD163+ TAMs in both tumor and stroma was strongly and significantly correlated with the absence of NANOG expression." (PMID 32630659, 2020). "These cells express the stemness genes OCT4, NANOG and SOX2/4 67 and have been demonstrated to asymmetrically differentiate to produce cells with increased tumor initiation, immunosuppressive properties, decreased sensitivity to chemotherapeutics and enhanced stemness 68,69." (PMID 32194856, 2020). "Given these surprising results, we sought to examine NANOG protein localization across a panel of various tumor and non-tumor cell types." (PMID 32168958, 2020).
tumor (continued). "Importantly, the analysis of WT tumors revealed a significant upregulation of NANOG and POUF5F1 when compared with the original tumor cells under 2D culture conditions, confirming the high impact of the tumor microenvironment on promoting stemness." (PMID 32230715, 2020). "As already observed for D2, NANOG promotes SCC cells invasion and exacerbates tumor invasiveness." (PMID 32197405, 2020). "KLF4 wasdown-regulated in both tumor samples and mammospheres.Meanwhile, expression of NANOG was not changed inmammospheres, but it was down-regulated in tumors.Among EMT-related genes, CDH2, SNAIL1, TWIST1/2 andZEB1 were also overexpressed in mammospheres." (PMID 31376329, 2020). "Along with the finding that the centrosomal localization of NANOG/NANOGP8 was detected in various tumor and non-tumor cell types, these results provide the first evidence suggesting a common centrosome-specific role of NANOG." (PMID 32168958, 2020). "Interestingly, histologically normal mucosa from various patients (33.3%, 5/15 cases) also exhibited increased expression of NANOG and SOX2, showing comparable mRNA levels in both the tumor sample and the patient-matched normal tissue." (PMID 32635524, 2020). "Western blot detection showed that hsa_circ_0068307 knockdown downregulated c-Myc and the CSC-related proteins, NANOG, OCT-4, and Sox-2 in tumor tissues, which further validated the regulatory role of hsa_circ_0068307/miR-147/c-Myc in in vivo BCa xenograft model." (PMID 32398967, 2020). "We found expression of pluripotency factors OCT3/4, LIN28 and NANOG in the TCam-2-ΔSOX2/FOXA2 tumor tissues, but not of PRDM14, which is strongly upregulated in TCam-2 cells, which were reprogrammed to an EC-like cell fate." (PMID 31130628, 2019). "Consistent with this, we also found that positive NANOG expression was more frequent in pN0 tumors, early I-II stages, and the absence of tumor recurrences." (PMID 31484317, 2019). "IHC staining of H1299control primary tumours supported these results as NANOG and high levels of nuclear YAP1 are apparent in H1299control tumours, while the active Hippo pathway in H1299RASSF1A tumours retains the majority of YAP1 in the cytoplasm and no NANOG staining is discernable." (PMID 31268606, 2019). "In contrast, two tumours without NANOG suppression (H646 and H627) still showed induction of SYP and NSE, suggesting alternative pathways towards NE properties." (PMID 30820548, 2019). "Particularly, pharmacological inhibition of ERK5 using XMD8-92 reduced the rate of primary and secondary sphere formation, the expression of pluripotency transcription factors SOX2, NANOG, and OCT4, and the proportion of tumor cells with increased ALDH activity." (PMID 30774996, 2019). "In addition, a significantly higher expression of CSC-related genes (NANOG, OCT4, SOX2, KLF4) was found in spheroids formed from ascites-derived tumor cells, compared to monolayer cells by qPCR." (PMID 31212816, 2019). "Despite the fact that OCT3/4 and NANOG have shown a direct relationship with the tumor grade, their oncogenic nature in brain tumorigenesis has not been established yet." (PMID 29849920, 2018). "Although several studies have reported that NANOG and HMGA2 could regulate Snail2 to affect tumor invasion and metastasis, few studies have investigated the relationship between Snail2 and EMT in CRC, and its implications in tumor progression." (PMID 30541610, 2018).
tumor (continued). "Our very recent studies highlighted a new hypoxia-induced pathway in which NANOG activates BNIP3L expression, contributing to autophagy induction in hypoxic tumor cells and their resistance to killing by CTL further suggesting a link between hypoxia-induced resistance and autophagy-related stemness." (PMID 29312568, 2017). "Similarly in lip SCC, NANOG is expressed by three distinct putative CSC subpopulations, both within the tumor nests and the peritumoral stroma." (PMID 28626726, 2017). "Western blot analysis of ex vivo isolated tumors at day 35 after challenge demonstrated decreased levels of pFGFR, pERK and NANOG proteins among mice that received 0.5 mg/kg of SSR128129E, demonstrating achievement of successful in vivo delivery of SSR128129E to the tumor." (PMID 28092370, 2017). "Expressions of SOX2, OCT4, WNT, NANOG, ABCG2 and ALDH1A1 was assessed both at transcriptional and translational levels from spheroids and sorted populations of CD44+/24− and ALDH+ cells of CT-TNBC tumor (CSC) versus the whole tumor." (PMID 28835684, 2017). "Consequently, SOX2 was silenced in mammospheres, formed from human tumor tissues which resulted in down regulation of OCT4, NANOG, ALDH1A1, and most importantly, ABCG2 expression (p < 0.01), confirming a direct correlation of SOX2 with ABCG2." (PMID 28835684, 2017). "RT-PCR and densitometric quantification analysis was used to quantify mRNA expression of a panel of stemness genes (NANOG, OCT-4, SOX-2, KLF4 and C-MYC), in addition to the CSC-specific markers, CD133 and ALDH1, in a cohort of matched normal and tumor lung tissues from NSCLC patients (n=20)." (PMID 29069808, 2017). "Regardless, NANOG induced in both LAPC4 and LAPC9 is required to sustain AI tumor growth." (PMID 27867534, 2016). "When we counted the cells in the immunofluorescent images of the tumor tissues around necrotic areas, SOX2+ HIF-1α+ RNApII-S2P-/low cells and NANOG+ HIF-1α+ RNApII-S2P-/low cells accounted for 0–6.3% and 0–4.7% of the cells in the microscopic field, respectively." (PMID 26799577, 2016). "Both PDX subsets expressed additional stem cell markers (CD146/CD29/OCT4/NANOG/Nestin) but still contained non-CSC tumor cells." (PMID 26551931, 2016). "These oncospheres are characterized by SOX2, OCT4, NANOG and ALDHA1 mRNA expression, high colony formation efficiency, enhanced growth in soft agar and enhanced tumourigenic potential in vivo that recapitulates the parental tumour." (PMID 26270676, 2015). "One plausible explanation for the synergistic anti-tumor effects is that rapamycin and crizotinib share common AKT-mTOR axis and its down-stream target molecules, NANOG and OCT4, as these are considered to be essential for tumor maintenance in many malignancies." (PMID 26517679, 2015). "Furthermore, we found that 4EGI-1 selectively inhibits translation of mRNAs encoding proteins that are enhanced in CSC maintenance, proliferation and metastasis, such as NANOG, OCT4, c-MYC, cyclin D1, CXCR4, VEGF and c-MYB, in breast CSC tumor cells." (PMID 25115391, 2014). "SP cells exhibited greater tumor-initiating ability and higher expression levels of iPS cell-related genes (SOX2, POU5F1 and NANOG), indicating that SP cells derived from LHK2, SW480 and MCF7 cells are enriched with CSCs/CICs and are a reasonable source for further research." (PMID 24244262, 2013). "NANOG promoter methylation levels were significantly reduced in the paired HCC tumors compared with adjacent non-tumor tissues (p = 0.000), whereas no significant changes were detected between normal and non-tumor liver tissues (p = 0.301)." (PMID 24023739, 2013). "DKK3 down-regulated stem markers such as NANOG, ABCG2 and OCT4, thus may reverse the stem cell-like phenotype of tumour cells." (PMID 23890219, 2013).